RN7SL338P (RNA, 7SL, cytoplasmic 338, pseudogene)
Gene: Miscellaneous RNA gene on chromosome 9 (35,049,271 to 35,049,563, forward strand). Ensembl gene ENSG00000241568.
Homologues: Orthologues: chimpanzee Metazoa_SRP (98% identical), macaque Metazoa_SRP (88% identical). Paralogues in human: RN7SL2 (77% identical), RN7SL1 (76% identical), RN7SL3 (76% identical), RN7SL126P (75% identical), RN7SL336P (74% identical), RN7SL220P (74% identical), RN7SL566P (74% identical), RN7SL28P (73% identical), RN7SL296P (73% identical), RN7SL357P (73% identical), RN7SL431P (73% identical), RN7SL44P (73% identical), and 700 more.